TRPA1 (transient receptor potential cation channel subfamily A member 1)
Diseases named in the same sentence as TRPA1 in open-access papers (continued):
Sharing a sentence is not in itself a finding about the gene and the disease.
respiratory diseases (continued). "Although there is no TRPA1 antagonist in advanced clinical trials or approved on market yet to treat respiratory diseases, however, limited but promising evidences available so far indicate likelihood that targeting TRPA1 may present a new therapy in treatment of respiratory diseases in near future." (PMID 27827953, 2016). "Thus, TRPA1 ion channel with its wide range of expression in neuronal and non-neuronal cells and its activation by several exogenous and endogenous stimuli relevant to airway sensory responses may be a major regulator in driving several respiratory diseases." (PMID 27827953, 2016). "Thus, the decrease in TRPA1, TRPV1, and MUC5AC in the lungs following the administration of LM extract should improve respiratory disease symptoms, such as cough and mucus production, in mice." (PMID 39519565, 2024). "Among them, TRPA1, the only member of the TRPA subfamily, is currently one of the most promising and studied targets in preclinical biological research, especially in the context of chronic and acute pain and respiratory diseases." (PMID 35630553, 2022). "Moreover, one of TRPA1 inhibitor, GRC-17536 has been used in phase II clinical trials in the treatment of respiratory disorders and diabetic peripheral neuropathy (NCT01726413)." (PMID 35720191, 2022). "Even though several patents have been filled for novel TRPA1 antagonists in respiratory disease, there are currently no clinically approved TRPA1 inhibitors." (PMID 33557843, 2021). "There is no TRPA1 antagonist in advanced clinical trials or approved on market yet to treat respiratory diseases." (PMID 27827953, 2016). "Hence, TRPA1 antagonists such as GRC 17536, which have started to show promising clinical benefits in human pain proof of concept trials, could also be effective in treating respiratory diseases." (PMID 27827953, 2016).
infection (16 papers, 2016 to 2025). The state of being infected such as from the introduction of a foreign agent such as serum, vaccine, antigenic substance or organism. "Furthermore, TRPA1 signaling in vagal afferents has been implicated in inhibiting cytokine release, inducing hypothermia, and reducing mortality from infection, highlighting its protective role." (PMID 38731999, 2024). "Additionally, direct activation of TRPA1 using optopharmacology and chemogenetic methods attenuates TNF production, whereas deletion of TRPA1 or interrupting afferent vagus nerve signaling results in a loss of these anti-inflammatory effects and decreases survival from infection." (PMID 36650454, 2023). "LPS suppresses feeding and egg-laying behaviors in Drosophila to prevent infection by stimulating gustatory neurons via a TRPA1-dependent cation channel." (PMID 39761205, 2025). "Vagus nerve TRPA1 signaling inhibited cytokine release, inducing hypothermia and reducing mortality due to infection." (PMID 38731999, 2024). "This would be consistent with the broad role of TRPA1 in inflammation, infection and immunity observed across a range of tissues." (PMID 28424320, 2017). "Infection with pathogenic microbes leads to the activation of TRPV1 and transient receptor potential cation channel subfamily A member 1 (TRPA1), which are enriched in the peptidergic nerve terminals, and mediate the Ca2+-dependent release of neuropeptides causing neurogenic inflammation." (PMID 37122730, 2023). "TRPA1 nociceptors are activated by diverse chemicals, reactive oxygen species, electrophilic compounds, temperature changes, and inflammatory mediators, and also by lipopolysaccharide (LPS), a bacterial endotoxin produced during infection." (PMID 36650454, 2023). "The present data now reveal the role of TRPA1 as also pleiotropic in mediating protective, homeostatic mechanisms in inflammation and infection because the results indicate an important role for vagus nerve TRPA1 ion channels in activating the thermoregulatory responses to IL-1β." (PMID 36650454, 2023). "Since TRPA1 is expressed in gut entero-endocrine cells were it mediates the effect of bacteria cell wall component, lipopolysaccharide, we tested if these specific gut cells are required for egg-laying response to infection." (PMID 28264763, 2017). "Thus, IL-1β activates TRPA1 vagus nerve signaling in the afferent arm of a reflex anti-inflammatory response which inhibits cytokine release, induces hypothermia, and reduces the mortality of infection." (PMID 36650454, 2023). "Thus, IL-1β activates TRPA1 vagus nerve signaling in the afferent arm of a reflex anti-inflammatory response to inhibit cytokine release, induce hypothermia, and reduce the mortality of infection." (PMID 36650454, 2023). "Therefore, we determined whether nociceptive-related genes, including TRPA1, ppk, AstA-R1, AstC-R1, and AstC-R2, were upregulated during bacterial infection and whether the expression of these genes differed upon infection." (PMID 29760446, 2018). "Up-regulation of TRPV1, TRPA1 and ASICS3 expression occurred by 12 hours post-infection in each cell type." (PMID 28187208, 2017). "TRPA1 activity due to LPS exposure leads to robust defensive behaviours, yet the long-term consequences on infection outcomes or surrounding non-sensory tissues remain to be investigated." (PMID 30103489, 2018). "Surface labelling of TRPA1 after shRNA treatment was performed similarly except using TGNs not subjected to infection with lenti TRPV1-DsRed." (PMID 26888187, 2016). "Non-neuronal implications of TRPA1 include inflammation, infection, and immunity." (PMID 32727091, 2020). "Disruption of the TrpA1–neuropeptide (DH31, a Drosophila secreted factor) pathway in EECs (ProsGal4>UAS-TrpA1RNAi or UAS-DH31RNAi) did not decrease survival or bacterial clearance during P.e. infection." (PMID 40950032, 2025).
cardiovascular diseases (11 papers, 2018 to 2025). "Recent studies have implicated transient receptor potential ankyrin 1 (TRPA1) channels, known for their role as sensory receptors, in the pathogenesis of cardiovascular diseases." (PMID 39323758, 2024). "Further research is needed to clarify the exact molecular mechanisms underlying TRPA1-mediated fibrotic remodeling and to translate these findings into clinically relevant therapeutic strategies for improving patient outcomes in cardiovascular diseases." (PMID 39323758, 2024). "In conclusion, the activation of TRPA1 indirectly reduces the incidence of cardiovascular diseases caused by glucose and lipid metabolism disorders." (PMID 32903613, 2020). "Moreover, we explore the challenges and opportunities linked with targeting TRPA1 channels for treating cardiovascular diseases, alongside future research directions." (PMID 39323758, 2024). "TRPA1 closely relates to many risk factors of cardiovascular disease." (PMID 32903613, 2020). "Moreover, this review summarizes some evidence that TRPA1 is correlated to cardiovascular disease risk factors." (PMID 32903613, 2020). "Finally, this paper presents some evidence that TRPA1 is closely linked to cardiovascular disease risk factors." (PMID 32903613, 2020). "Using TRPA1 KO mice, Pozsgai showed that TRPA1 causes cardiovascular effects by influencing some cardiovascular effects but this was difficult to define in terms of relevance to cardiovascular disease using TRPA1 knockout mice." (PMID 29164310, 2018). "The therapeutic response to TRPA1 agonists or antagonists may be dependent on the expression level or profile of the TRPA1 protein, therefore, future studies may need to identify specific variants that potentially regulate the expression of TRPA1 in cardiovascular diseases." (PMID 39323758, 2024). "Unlike previous reviews, this article focuses on the role of TRPA1 in the development of cardiovascular diseases." (PMID 39323758, 2024). "While targeting TRPA1 channels holds promise as a therapeutic approach for cardiovascular diseases, further research is needed to elucidate their precise roles and regulatory mechanisms." (PMID 39323758, 2024). "Comprehensive clinical trials are warranted to evaluate the safety and efficacy of TRPA1-targeted therapies in patients with cardiovascular disorders, paving the way for the development of innovative treatments for these debilitating conditions." (PMID 39323758, 2024). "Several TRPA1 agonists and antagonists have been testing in recent and ongoing clinical trials in various disorders other than cardiovascular diseases." (PMID 39323758, 2024). "Future studies should focus on validating TRPA1 as a viable therapeutic target and exploring novel strategies to modulate TRPA1 activity for the treatment of cardiovascular diseases." (PMID 39323758, 2024). "We discuss the diverse roles of TRPA1 channels in cardiac pathology and highlight their potential as therapeutic targets for cardiovascular disorders." (PMID 39323758, 2024). "In conclusion, the mechanism in which oxidative stress products activate TRPA1-mediated cardiovascular disease needs to be further discussed." (PMID 32903613, 2020). "In recent years, research on TRPA1 has been increasing, hence a close relationship between TRPA1 and cardiovascular diseases is established." (PMID 32903613, 2020). "TRPA1’s role in cardiovascular diseases has received extensive attention, and it is directly or indirectly involved in the occurrence and development of cardiovascular diseases." (PMID 32903613, 2020). "This review introduces the structural and functional characteristics of TRPA1 and its importance on vascular physiology and common cardiovascular diseases." (PMID 32903613, 2020). "The transient receptor potential ankyrin 1 (TRPA1) channel is expressed in cardiomyocytes and involved in many cardiovascular diseases." (PMID 29682158, 2018).
cardiovascular diseases (continued). "This review focuses on the role of TRPA1 in the development of cardiovascular diseases rather than the underlying regulatory molecular mechanisms as they have been discussed in previous reviews." (PMID 39323758, 2024). "This aim included identifying potential cardiac side effects of TRPA1 agonists and antagonists that might be used as future pain medication, as well as therapeutic strategies for cardiovascular diseases." (PMID 33819369, 2021). "This review describes the role of TRPA1 channels in common cardiovascular diseases." (PMID 32903613, 2020). "Given the link between the TRPA1 channel and various cardiovascular diseases, it could be an attractive drug target for therapeutic interventions." (PMID 31680989, 2019). "However, the role of TRPA1 in cardiovascular diseases is uncertain." (PMID 32903613, 2020). "However, many researchers have not explored the role of TRPA1 as a potential target for the treatment of cardiovascular diseases." (PMID 32903613, 2020). "In addition, non-neuronal TRPA1 and TRPV1 play a role in cardiovascular disease, immunity and other conditions." (PMID 33804078, 2021).
neurodegenerative disease (6 papers, 2019 to 2026). A disorder of the central nervous system characterized by gradual and progressive loss of neural tissue and neurologic function. "The results will facilitate the development of novel synthetic multi-target drugs for peripheral neurodegenerative diseases targeting TRPA1 in Schwann cells." (PMID 36290569, 2022). "Since reactive astrocytes can contribute to the progression of neuroinflammation in neurodegenerative diseases, several workgroups, including ours, had started to investigate the role of TRPA1 in animal models of neurodegenerative diseases." (PMID 31905673, 2019). "TRPA1 is activated during periods of inflammation and oxidative stress, and therefore it is important that we understand whether it plays a role in demyelinating and neurodegenerative diseases." (PMID 36762504, 2023). "Therefore, these modulators of TRPA1 and TRPV1 have the potential for the development of new therapeutic agents for neurodegenerative disease treatment." (PMID 38203538, 2023). "Therefore, modulators of TRPA1 and TRPV1 have the potential for the development of new therapeutic agents for the treatment of neurodegenerative diseases." (PMID 38203538, 2023).
neurological diseases (5 papers, 2016 to 2024). "The TRPA1 protein plays a key role in the transmission of pain signals and sensitivity to cold, and its mutations correlate with the occurrence of various neurological diseases, including chronic pain." (PMID 39684844, 2024). "Among these genes, Ch25h, Trpa1, Cdkn1a, Ly6g6e, Six3, and Opalin are potentially associated with neurological diseases; Lcn2, Serpina3f, Lao1, Trim29, bcl3, and Gkn3 are associated with inflammatory response." (PMID 30804943, 2019). "In recent years, the TRPA1 (Transient Receptor Potential Ankyrin 1) gene has attracted particular interest in the context of its involvement in the pathogenesis of neurological diseases." (PMID 39684844, 2024).
kidney disease (4 papers, 2021 to 2024). "Further studies using cell-specific TRPA1 deletion models are required to elucidate its functional significance in kidney diseases." (PMID 39273183, 2024). "The role of TRPA1 in kidney disease as mediator of neurogenic inflammation via sensory afferents has not been reported." (PMID 33810314, 2021). "A genetically modified mouse model with cell-specific deletion of TRPA1 is required to assess the functional role of TRPA1 in kidney disease." (PMID 33810314, 2021). "Recent studies have implicated TRPA1 in kidney disease and primarily addressed its effects on non-neuronal cells." (PMID 39273183, 2024). "In this review, we summarised the role of TRPA1 in neurogenic or non-neurogenic inflammation and in kidney disease, especially the non-neuronal TRPA1." (PMID 33810314, 2021). "The role of TRPA1 in kidney disease in published studies focused on the role of TRPA1 in non-neuronal cells." (PMID 33810314, 2021).
metabolic disorders (3 papers, 2021 to 2025). "TRPA1 channels, which are distributed throughout the body, are emerging as potential therapeutic targets for metabolic disorders and NPDs." (PMID 34912298, 2021). "In this review, we have tried to present evidence of the possible involvement of TRPA1 channels in neuropsychiatric and metabolic disorders and a possible hint towards using TRPA1 modulators to target appetite, lipid metabolism, glucose and insulin homeostasis and inflammation associated with NPDs." (PMID 34912298, 2021).
bacterial infection (2 papers, 2018 to 2024). "In this context, it is interesting to note that the ROS/TrpA1/Dh31 axis is shared between larvae and adults to manage bacterial infection, but larvae block and kill the pathogens while adults eject them." (PMID 39576741, 2024). "Results showed that genes coding for TRPA1, ppk, AstA-R1, AstC-R1, and AstC-R2 are upregulated during bacterial infection and this upregulation may lead to hyperalgesia." (PMID 29760446, 2018). "The aim of the current study was to characterize a panel of known nociceptive (TRPA1, ppk, AstA-R1, AstC-R1, AstC-R2) genes in Drosophila, and to determine if any of these genes impacted survivorship or immune function during bacterial infection." (PMID 29760446, 2018).
central nervous system diseases (2 papers, 2019 to 2023). "Therefore, TRPA1 participates in central nervous system diseases by regulating neural circuits and intracellular calcium homeostasis." (PMID 36875034, 2023). "Consequently, the pH dependency of TRPA1 may be beneficial target for the treatment of central nervous system diseases, not only pain." (PMID 31336748, 2019).
infectious disease (2 papers, 2022 to 2023). A disorder directly resulting from the presence and activity of a microbial, viral, or parasitic agent in humans. "The potential of TRPA1 in regulating various inflammatory pathways and its association with various intracellular proteins has provided insights toward TRPA1 targeted therapeutic development in various autoimmune disorders and infectious diseases." (PMID 37391696, 2023).
psychiatric diseases (2 papers, 2021 to 2023). "Thus, these lines of evidence suggest that TRPA1 is a negative regulator of brain functions, raising the possibility that there is a connection between TRPA1 expression or function and psychiatric disorders; however, further studies are required to validate this hypothesis." (PMID 33644051, 2021).
cardiac disease (1 paper, 2021). "Further, mounting evidence suggests that TRPA1 may be a key gatekeeper in regulating the inflammatory response and oxidative stress, and play an important role in the pathophysiology of cardiac disease." (PMID 33458442, 2021).
gastrointestinal disorders (1 paper, 2024). "The therapeutic implications of targeting TRPA1 in respiratory and gastrointestinal disorders are promising." (PMID 39022308, 2024).
genetic disorder (1 paper, 2023). "Familial episodic pain syndrome, a genetic disorder accompanied by episodic body pain, has been shown to be associated with a TRPA1 deficiency." (PMID 36982450, 2023). "In addition, the importance of TRPA1 in human pain sensation is indicated by a genetic disorder in which TRPA1 is affected." (PMID 36982450, 2023).
hematological malignancies (1 paper, 2017). "In the current study, the cross talk among the Notch1 pathway, Ets-1, and TRPA1 in erythroid and megakaryocyte differentiation suggests a potential combinatorial strategy for treatment of hematological malignancies in the near future." (PMID 28220825, 2017).
TRPA1 also shares sentences with these, for which no sentence is quoted: ulcerative colitis (6 papers); cerebral artery (3); migraine aura (3); bronchitis (2); complex regional pain syndrome (2); deglutition disorders (2); diabetic polyneuropathy (2); erythromelalgia (2); functional dyspepsia (2); headache disorder (2); invasive ductal breast carcinoma (2); oral squamous cell carcinoma (2); acute cystitis (1); acute myocardial infarction (1); age (1); agranulocytosis (1); anaplastic astrocytoma (1); animal disease (1); Anosmia (1); atopic asthma (1); bladder disorders (1); brain disorder (1); bullous pemphigoid (1); cancers of the skin (1); Candida infection (1); cardiac arrhythmias (1); cerebrovascular diseases (1); cholangiocarcinoma (1); Chronic pain (1); Cluster headache (1).
A further 59 diseases each share a sentence with TRPA1 in 1 paper.